MBP (myelin basic protein)
Diseases named in the same sentence as MBP in open-access papers (continued):
Sharing a sentence is not in itself a finding about the gene and the disease.
Moyamoya disease (1 paper, 2016). Moyamoya disease (MMD) is a rare intracranial arteriopathy involving progressive stenosis of the cerebral vasculature located at the base of the brain causing transient ischemic attacks or strokes. "On multivariate logistic analysis, an operation on the dominant hemisphere, female gender, and minimum MBP in ward were significantly associated with the development of postoperative CHS after STA-MCA anastomosis in patients with moyamoya disease." (PMID 28033272, 2016).
myeloma (1 paper, 2014). "In samples of femurs exhibiting an intermediate myeloma load where individual myeloma cells and small clusters of myeloma cells were detectable, co-localization between myeloma cells, MBP+ eosinophils and CD41+ megakaryocyte lineage cells was studied." (PMID 25272036, 2014).
Neonatal sepsis (1 paper, 2020). Systemic inflammatory response to infection in newborn babies. "In these reports, the authors investigated the therapeutic effect of MSCs or MSC-derived extracellular vesicles on MBP expression using a PVL model created by exposure of 3- or 4-day-old rats to LPS, similar to our neonatal sepsis model." (PMID 33339379, 2020).
pancreatic cancer (1 paper, 2025). "Blood exosomes from 18 pancreatic cancer patients and 16 healthy controls were collected for detection of miR-21, miR-191, and miR-451a by molecular beacon–peptide (MBP) probes, showing increased expression of these miRNAs in pancreatic cancer patients." (PMID 40075875, 2025).
parasitic infection (1 paper, 2017). "Treatment with NDS61 mAb to deplete CD25+ cells before immunization with MBP/CFA reduced the protective effect of parasitic infection on EAE." (PMID 29163523, 2017).
Parkinson disease 2 (1 paper, 2022). "Our results identified genes such as neurexin 3, Parkinson disease 2, myelin basic protein (MBP), neuron-specific enolase (NSE), and leucine-rich repeats and calponin homology domain containing 1 (LRCH1) which were associated with DEACMP." (PMID 35140817, 2022).
peripheral nerve injury (1 paper, 2015). Injury to a peripheral nerve. "In the present study, we studied the effects of immunization with MBP-derived APL on pain behavior and neuroinflammation in an animal model of peripheral nerve injury." (PMID 25885812, 2015).
peroxisomal disorders (1 paper, 2020). "At advanced stages, many peroxisomal disorders exhibit axon demyelination, which was not clearly obvious in immunofluorescence images against MBP." (PMID 33244184, 2020).
phenylketonuria (1 paper, 2015). Phenylketonuria (PKU) is the most common inborn error of amino acid metabolism and is characterized by mild to severe mental disability in untreated patients. "Numerous GFAP(+)/MBP(+) cells are reported in a mouse model of phenylketonuria, which is associated with central hypo-mylination, and there is strong evidence for astrocyte production from NG-2 cells following traumatic injury, ischemia and spinal cord injury." (PMID 26106302, 2015).
polyneuropathy (1 paper, 2021). A disease or disorder affecting more than one nerve. "Immunofluorescent staining of myelin basic protein in polyneuropathy patients reached only approximately 20% of levels measured in the control group." (PMID 34735549, 2021). "The reduction of myelination as measured by myelin basic protein staining and histomorphometric analysis of nerve cross-sections was even more apparent, indicating significant Schwann cell dysfunction in polyneuropathy patients." (PMID 34735549, 2021). "Our results showed a highly significant reduction of myelin basic protein in polyneuropathy patients compared to controls." (PMID 34735549, 2021). "The myelination parameter myelin basic protein was drastically reduced from 37.93% ± 5.85 (range: 29.39 to 42.08) in controls to 7.6% ± 5.4 (range: 1.57 to 19.05) in polyneuropathy patients (p = <0.001)." (PMID 34735549, 2021).
prion disease (1 paper, 2024). A transmissible disease that is caused by a protein that is able to induce abnormal folding of normal cellular proteins, leading to characteristic spongiform brain changes, which are associated with neuronal loss without an inflammatory response. "In prion disease, an antibody raised against citrullinated MBP showed a punctate staining pattern in white matter, which could be MBP aggregates similar to what was observed in ALS." (PMID 39712644, 2024).
progressive ataxia (1 paper, 2014). "Mice that lack MBP have a characteristic motor dysfunction including tremor and seizures, mice that lack Caspr have severe motor paresis whereas mice lacking cerebellar ankG develop progressive ataxia." (PMID 24685353, 2014).
prostate tumours (1 paper, 2023). "The MBP gene encodes the myelin basic protein, which is a constituent of the myelin sheath, and has no obvious role in PCa, however, mouse model studies have shown that neural progenitor cells can invade prostate tumours, triggering neurogenesis and promoting tumour growth and metastasis." (PMID 38052806, 2023).
retina degeneration (1 paper, 2009). "We evaluated the NGF effect on optic nerve and retina degeneration by estimating the number of ganglion cells 75 days after 2VO legation, and by measuring the optic nerve diameter, and the beta-tubulin- and MBP-immunostained area fraction over the optic nerve transverse section." (PMID 19473529, 2009).
retinal ischemia (1 paper, 2016). A ischemic disease that involves the retina. "Retinal ischemia highly induced an increase of Tregs proliferation, which was more prominent in MBP-immunized animals." (PMID 27886260, 2016).
Sanfilippo disease (1 paper, 2023). "This analysis confirmed that the amount of MBP was significantly reduced in cortices from all three MPS patients, suggesting that demyelination may be a hallmark common for most subtypes of Sanfilippo disease." (PMID 38163061, 2023).
scoliosis (1 paper, 2023). A congenital or acquired spinal deformity characterized by lateral curvature of the spine. "Next, we demonstrated that the blood exosomal test can diagnose CP/scoliosis by assaying molecular markers (e.g., low levels of MBP mRNA and protein, and low levels of FFAR) in cell type-specific exosomes." (PMID 37538811, 2023). "Here, OL marker, MBP gene and protein expression in OL-Es isolated from healthy controls, CP/Scoliosis, Scoliosis and CP alone, was downregulated most in both CP/scoliosis cases." (PMID 37538811, 2023). "FFAR and MBP proteins were downregulated in each of the three patient groups compared to controls, and this difference was greatest in both patients with CP plus scoliosis." (PMID 37538811, 2023). "As far as we know, these are the first two clinical cases of CP and scoliosis that have been studied for OL marker, MBP, and FFAR using OL-derived exosomes." (PMID 37538811, 2023). "Both ddPCR and ELISA on exosomes isolated from the plasma revealed strong downregulation of MBP also in OL-Es of CP/scoliosis patients." (PMID 37538811, 2023). "Our studies investigated involvement of FFAR and MBP in CP/scoliosis cases." (PMID 37538811, 2023). "We, first, studied OL marker, MBP, in plasma of patients with CP and scoliosis to assess whether OLs were affected in CP/scoliosis patients." (PMID 37538811, 2023). "Downregulation of MBP in OL-Es from patients with CP/scoliosis." (PMID 37538811, 2023). "Levels of MBP gene expression and MBP protein were lowest in patients with CP/scoliosis." (PMID 37538811, 2023). "Thus, both CP/scoliosis patients had lowest levels of OL MBP and FFAR." (PMID 37538811, 2023). "Studies on MBP and FFAR may explain how fatty acids influence lipid metabolism at a molecular level in humans in CP and scoliosis." (PMID 37538811, 2023). "In the present study we describe changes in MBP and FFAR in two cases with CP and scoliosis." (PMID 37538811, 2023). "Altogether, MBP and FFAR levels were reduced in OL-Es from both children with CP plus scoliosis." (PMID 37538811, 2023).
sleep disorder (1 paper, 2021). A change from the patient's baseline sleeping pattern, in the hours slept and/or an alteration/dysfunction in the stages of sleep. "A variant in the MBP gene was found in patient I, who presented hand stereotypies, hyperactivity, sleep disorder, and speech delay." (PMID 34948243, 2021).
sleeping sickness (1 paper, 2023). "Consistent with the data obtained from CSF biopsies, we observed that sleeping sickness patients with an active infection have significantly higher titres of serum IgG against MBP compared to healthy African controls." (PMID 37983289, 2023). "To further validate our findings, we examined the presence of circulating antibodies against MBP in an independent cohort of sleeping sickness patients from DRC that included both patients with an active infection (“cases”) and samples obtained from patients posttreatment (“treated)." (PMID 37983289, 2023).
thyroid (1 paper, 2025). "When thyroid toxicity drastically reduces ATP synthesis, these high-metabolic-demand tissues face endoplasmic reticulum stress, hindering the synthesis of myelin basic protein." (PMID 41357835, 2025).
toxoplasmosis (1 paper, 2021). A parasitic disease contracted by the ingestion or fetal transmission of toxoplasma gondii. "Although functional roles of MBP derived peptides are unknown, they are likely involved in physiological and behavioral processes during toxoplasmosis." (PMID 34367142, 2021).
ulcerative colitis (1 paper, 2021). An inflammatory bowel disease involving the mucosal surface of the large intestine and rectum. "This research aimed to explore the effects of milk‐based protein (MBP), potato protein (PP), and mixed protein (MP) on the recovery of mice with dextran sulfate sodium (DSS)‐induced ulcerative colitis (UC)." (PMID 33747442, 2021).
X-linked intellectual disability (1 paper, 2025). An X-linked intellectual deficiency in which not enough information is known, reported or published to indicate whether a gene causes non-syndromic or syndromic presentations. "ZDHHC9 palmitoylates myelin basic protein (MBP) in cultured cells and in vivo, and certain ZDHHC9 X-linked intellectual disability (XLID) mutants display residual protein acyltransferase (PAT) activity towards MBP." (PMID 41031565, 2025).
ZIKV infection (1 paper, 2021). "Among the top selected differentially expressed genes, such as PTBP1, LIF, GHR, PTBP3, EDNRB, and MBP, the mRNA and protein expressions were confirmed to identify the dysregulation of the transcriptome in MPAs upon ZIKV infection." (PMID 33891593, 2021). "Our results showed that mRNA levels of PTBP1, LIF, PTBP3, and GHR were significantly upregulated, while EDNRB and MBP were downregulated upon ZIKV infection at indicated time." (PMID 33891593, 2021). "We found that PTBP1, LIF, GHR, and PTBP3 were upregulated while EDNRB and MBP were downregulated upon ZIKV infection." (PMID 33891593, 2021).
tumor (48 papers, 1974 to 2025). "Myelin basic protein (MBP) staining shows extensive myelin loss in control tumors, while treated sections exhibit better preservation of myelin integrity, indicating reduced tumor‐associated damage." (PMID 40249282, 2025). "At D9, coDbait with RT induced a substantial loss of MBP labeling surrounding the tumor, presumably due to a destabilization of striosomes (white arrow)." (PMID 22815765, 2012). "The present experiments demonstrate an antigenic determinant in murine tumours, similar to the well-characterized EAE peptide of human MBP, and establish an animal model for study and characterization of common tumour-associated antigens." (PMID 6177329, 1982). "To verify the importance of long fragments as containing tumor-derived DNA, we separated short and long plasma DNA fragments using agarose gel electrophoresis and examined the presence of L858R mutation by the MBP-QP method." (PMID 29861862, 2018). "Some DEGs like FREM2, ANXA2 and GPC4 revealed common enrichment in LE/IT tumor regions across GBM patient samples compared to the overall downregulation of the OPC/OL marker MBP, the neural marker NTRK2, and the ECM glycoprotein EDIL3." (PMID 41366031, 2025). "In contrast, tumors had completely disappeared in 1 out of 6 animals in the MBP-11901 group; 1 had only a trace of a tumor measuring approximately 30 mm3, whereas the average tumor volume in the 6 animals was approximately 100 mm3." (PMID 35454900, 2022). "To confirm the antitumor effect of MBP-11901 in vivo, we generated a HepG2 xenograft tumor model in BALB/c nude mice." (PMID 35454900, 2022). "We thus performed Transwell assays to determine the effect of MBP-11901 on the migration and invasion ability of tumor cells." (PMID 35454900, 2022). "Histological analysis of MBP-11901-treated tumor masses revealed a decrease in the levels of proliferation proteins and an increase in those of apoptosis proteins." (PMID 35454900, 2022). "Analysis of the expression of Ki-67 and cleaved caspase-3 in tumors treated with MBP-11901 showed a significant reduction in the proliferation of tumor cells, and a high level of apoptosis compared with the vehicle control." (PMID 35454900, 2022). "Among these genes, six (HOXA6, STC2, HSD17B8, TFAP2A, CYP1B1, and HOXC8) were reported to be osteogenesis-/chondrogenesis-related genes, and five (ADRA1A, TSPYL5, TES, TNFRSF10D, and MBP) were reported to be tumor-suppressor genes." (PMID 31889115, 2019). "Immunohistological analysis of MBP-positive myelin elements showed that RT alone preserved the structure of striosomes around the tumor." (PMID 22815765, 2012). "Mice bearing a methylcholanthrene-induced tumour were tested for their cell mediated reactivity to the experimental allergic encephalomyelitis (EAE) peptide of human myelin basic protein (MBP) in the leucocyte adherence inhibition (LAI) test." (PMID 6177329, 1982). "To assess if demyelination occurred throughout the normal brain after treatment with the combination, we assessed MAG and MBP expression via IHC using both RA-055 xenograft tumors collected at endpoint and tumor naive C57BL/6J mice, treated with the combination for 4-weeks." (PMID 38319732, 2024). "Genes critical to oligodendroglial myelination, including myelin-associated glycoprotein (MAG), myelin basic protein (MBP), and myelin oligodendrocyte glycoprotein (MOG), showed significantly decreased expression in tumor tissue following 4-week treatment with the combination." (PMID 38319732, 2024). "Similarly, we observed that tumor weights per mouse in the 40, 60, and 82 mg/kg MBP-11901-treated groups were 0.082 ± 0.063, 0.025 ± 0.035, and 0.011 ± 0.009 g, respectively, compared with 0.31 ± 0.089 g in the vehicle control group." (PMID 35454900, 2022). "MBP-11901 highly inhibited the migration and invasion of tumor cells in a dose-dependent manner." (PMID 35454900, 2022).
tumor (continued). "In addition, SOX10+ cells were lowly proliferative, progressed to a CNP+/CC1+/MBP− immature pre-oligodendrocyte state and were restricted to MBP+ tumour regions." (PMID 33846316, 2021). "In addition, mice treated with EBP‐ or MBP‐MPC‐NP for 21 days showed 75% reduction in tumor volume to 50 mm3, further demonstrating the enhanced anti‐tumor effect of combination therapy." (PMID 34085418, 2021). "Additionally, Leu-7 (CD-57) and myelin basic protein are used frequently to assess neural differentiation of a neoplasm, noted in 50% and 40% of cases, respectively." (PMID 24392233, 2013). "Besides Pmp22, it is highly possible that other RUNX1/3 targets, such as SDC4, ERN1, and/or MBP, might be involved in tumor formation." (PMID 31032403, 2019). "We evaluated the growth structures using multiplexed immunofluorescence staining, employing STEM121 to identify tumor cells, and specific markers such as CD31 for blood vessels, MBP for white matter, AQP4 for astrocytes, and NeuN for neurons." (PMID 40683881, 2025). "We found that the expression of 9 DE-ceRNAs were significantly different between tumor tissues and normal tissues, including the upregulated H19, HOTAIR, miR222, miR148a, PCDHGB4, GMNC and HMGA2 and the downregulated LRP2 and MBP in tumors." (PMID 40351420, 2025). "To identify such contexts, we co-stained each protein of interest with markers for tumor cells (anti-human STEM121/NCL), blood vessels (CD31), and white matter (MBP)." (PMID 40683881, 2025). "As expected, OPC markers OLIG2, SOX9, and cell cycle genes CDK1, MKI67 are highest in the tumor core (early peak), while neuronal markers ZIC1, GABRA1, and mature oligodendrocyte marker MBP are highest in the GCL_N (late peak)." (PMID 36823172, 2023). "ROBO1, KLK6, LIMK2, KLK7, NLGN4X, MBP, and NEDD9 expression levels were significantly higher in normal tissues than in tumors, demonstrating the possibility of being a tumor suppressor gene." (PMID 38137332, 2023). "We confirmed the restriction of SOX2 expression to tumor cells, PTPRC/CD45 to immune cells, SPI1/PU.1, CD68, and CD163 to ‘macrophages’, CD3G to ‘T cells’, and OLIG1/2 and MBP to oligodendrocytes." (PMID 35973991, 2022). "Eosinophils are activated by IL33, IFN-γ, and IL-5, and activated eosinophils secrete MBP, tumor necrosis factor (TNF)-α, eosinophil peroxidase, and granzyme B, which facilitate the killing of tumor cells." (PMID 35011007, 2021). "We studied 80 primary and 12 metastatic ccRCC tumors and identified 7 peptide substrates with significantly increased tyrosine phosphorylation by metastatic samples relative to primary tumor samples including FGFR1, FAK1, ACHD, K2C8, EGFR, EPHB4 and MBP." (PMID 28418903, 2017). "Notably, the RPL29 and MBP fragment peptides 135–149 and 168–177, respectively, are listed in SPENCER as tumor-specific for various cancers, suggesting their potential as novel neoantigens for immunotherapeutic strategies." (PMID 40649831, 2025). "Treatment decreased expression of MBP and MAG in RA-055 xenograft tissue in line with the UON-VIBE5 model, however, expression did not change in normal mouse brain tissues, suggestive of a tumor-specific effect." (PMID 38319732, 2024). "As control, stainings of ENPP6, MBP and LFB were observed in the non-tumour regions." (PMID 38764775, 2024). "The differential gene expression levels between the tumor and adjacent tissue indicated that the ROBO1, KLK6, LIMK2, KLK7, NLGN4X, MBP, and NEDD9 gene expression levels were higher in normal tissues than in tumors; however, EFNA1 was higher in the tumor than the normal ones." (PMID 38137332, 2023). "At 4 weeks, the intensity in the saline group was increased by 26.92 ± 30.3-fold and in the Nexavar® group by 11.69 ± 10.0 fold, whereas in the MBP-11901 group it was decreased by 0.02 ± 0.0-fold, so that almost no tumor bioluminescence was measured." (PMID 35454900, 2022).